MYC (MYC proto-oncogene, bHLH transcription factor)
Diseases named in the same sentence as MYC in open-access papers (continued):
Sharing a sentence is not in itself a finding about the gene and the disease.
cancer (continued). "Recently, we found that a major oncogene in cancer, MYC, is deregulated in MRT and that rSWI/SNF subunits colocalize extensively with MYC on chromatin, providing the first links between rSWI/SNF complexes and oncogene function." (PMID 35650187, 2022). "For instance, the MYC TFs are among the most commonly dysregulated driver proteins in an overwhelming majority of human cancers." (PMID 35267473, 2022). "While driving tumorigenesis, the overload of biosynthetic and metabolic activities activated by MYC elicits diverse forms of oncogenic stress, which impact on cancer initiation, progression and maintenance, as well as on the response to therapy." (PMID 36214609, 2022). "In cancer cell-free EC-adjacent tissues (TA), the expression of MYC, NR5A2, SNAI1, and CXCR2 was higher than in Ctrl samples." (PMID 36140779, 2022). "In sum, PRMT5 is a therapeutic target in PDAC, and high mRNA expression of the arginine methyltransferase marks cancers with high MYC expression and network activity." (PMID 35439169, 2022). "In the pathogenesis of cancer, MYC induces cancer growth by modulating cellular proliferation, protein synthesis, DNA replication, cellular metabolism, and other processes." (PMID 35370699, 2022). "The overexpression of c-MYC can rewire the gene expression profile to sustain the demands of cancer cells, enhanced ribosome biogenesis being one of them." (PMID 35267559, 2022). "Among them, the proto‐oncogene MYC (also known as c‐MYC) attracts our attention, since MYC activation contributes to the occurrence of diverse cancers, and MYC inhibition induces senescence in a variety of cancer cells." (PMID 34687270, 2022). "Due to its critical role in cell growth/proliferation, one of the most well-known cancer-promoting proteins is MYC." (PMID 35741402, 2022). "Previous preclinical studies of BET and PARP inhibitors have largely focused on cancer cell lines with MYC amplification." (PMID 36227363, 2022). "Take together, the findings of this study provide a valuable reference to revealing the mechanism of cancer-promoting action of MYC in LUAD." (PMID 36299592, 2022). "MYC over expression is very common in several diagnosed types of cancer in which it is expressed constitutively." (PMID 36544623, 2022). "Nevertheless, the link between the transporter SLC1A5 and oncogenic MYC expression and adverse prognosis in a variety of cancers prompted the development of the SLC1A5 inhibitor as a target of pharmacological blockage." (PMID 36499623, 2022). "In conclusion, MYCMI-7 is a potent and selective MYC inhibitor that is highly relevant for the development into clinically useful drugs for the treatment of MYC-driven cancer." (PMID 36874405, 2022). "It has been reported that E6 modulates the expression of some important genes in cancer through proteins such as MYC." (PMID 35632705, 2022). "MYC protein levels are tightly regulated by the proteasome and an increase in MYC protein expression is found in more than 70% of all human cancers, including MM." (PMID 35625675, 2022). "The high expression of MYC promotes the occurrence, development and maintenance of tumors, and is related to aggressive cancer and poor prognosis." (PMID 35645616, 2022). "Overall, our results provide insights into the dynamic processes that control c-MYC levels and support the potential of perturbing these mechanisms in cancer." (PMID 36230763, 2022).
cancer (continued). "Here we show that OM-153 is a highly potent and specific inhibitor of TNKS1/2, WNT/β-catenin, YAP and MYC signaling capable of reducing cell growth in a subset of human cancer cell lines." (PMID 36873622, 2022). "Dicerna Pharmaceutical developed DCR-MYC, a lipid particle with double-stranded RNA targeting the MYC oncogene and suppressing cancer progression." (PMID 35681657, 2022). "Among tuft-cell-like cancers, the percentage of MYC-positive cells and the Ki-67 labeling index were significantly higher in NECs than SQCCs (both P < 0.05)." (PMID 36402755, 2022). "MDA-MB-231, in particular, is a highly metastatic TNBC cell line with pronounced MYC-driven cancer stem cell features." (PMID 36207293, 2022). "Using the chromosome conformation capture (3C) technique, researchers have found long-range physical interactions between eRNAs from 8q24 and MYC, whose dysregulation is a significant symbol of multiple cancer types." (PMID 36232885, 2022). "The MYC gene consists of three sub-branches, namely, C-MYC, N-MYC, and L-MYC, and is one of the most common runaway driver genes in human cancers." (PMID 35996406, 2022). "MYC is a well-documented transcription factor that is extensively involved in stem cell biology cancer." (PMID 36034872, 2022). "The proto-oncogene MYC is highly overexpressed and/or amplified in human cancers and transcriptionally activates ODC1; thus, polyamine metabolism is an attractive cancer therapeutic target." (PMID 35736351, 2022). "The Mtorc1 and MYC signaling pathways, which lead to high metabolism and proliferation of cancer cells, were considerably enriched." (PMID 35967424, 2022). "As a result, expressions of two target genes of β-catenin, namely CCND1 and MYC, which are important for cancer proliferation, were suppressed." (PMID 36336731, 2022). "Among the well-recognized cancer drivers, MYC appeared to be affected by several recurrent genetic aberrations in CLL." (PMID 34417556, 2022). "Over 70% of all human cancers show elevated MYC levels and B-cell specific MYC expression in mice initiates BCL with full penetrance." (PMID 35022408, 2022). "The 8q21-24 region homes overexpressed oncogenes, such as MYC, heat shock factor 1 (HSF1), and associated cancer signatures." (PMID 36497066, 2022). "One of the most well-studied oncogenes is the transcription factor MYC, which is overexpressed in more than half of all cancers." (PMID 34937878, 2022). "Through these multiple mechanisms, MYC can drive a dramatic increase in rRNA production, contributing to ribosome biogenesis in cancer cells." (PMID 35159381, 2022). "MYC gene amplification and translocation cancers are particularly aggressive and challenging to treat, owing to the undruggable nature of Myc protein." (PMID 35720131, 2022). "As one of the common oncogenes, c-MYC is closely related to the prognosis, occurrence and development of cancer." (PMID 36233342, 2022). "A recent study demonstrated that the m6A reader YTHDF2 specifically stabilizes MYC mRNA in cancer stem cells and that YTHDF2 provides a therapeutic target to interfere with MYC signaling in GBM." (PMID 35265626, 2022). "The MYC gene family serves as an important regulator of tumorigenesis and includes three members, namely, c-Myc, N-Myc, and L-Myc, of which c-Myc is highly expressed in a variety of cancers and functions as a proto-oncogene." (PMID 36293081, 2022). "These same processes are deregulated in MYC‐driven tumors, where they become critical for cancer cell proliferation and survival." (PMID 36214609, 2022). "On one hand, recent evidence uncovered a widespread role for MYC in therapy resistance in multiple cancer types, with either standard chemotherapeutic or targeted regimens." (PMID 36214609, 2022). "GO analysis and GSEA revealed disruption of MAPK, E2F and MYC pathways, echoing two very recent studies also reporting KIF26A’s involvement in MYC and E2F pathways in cancer." (PMID 36228617, 2022).
cancer (continued). "We recognized that both the GSDMD and HSF1 genes are 889.264 kb apart on the same locus on 8q.24 and 15,810.256 kb downstream from one of the most overexpressed oncogenes in human cancer, the MYC chr8 (127735434-127742951)." (PMID 36497066, 2022). "As an example, inducing G4 structures within the oncogene promoter MYC blocks the expression of MYC, a transcription factor that is upregulated in 70% of cancers, altering cell proliferation, metabolism and immune evasion." (PMID 36428499, 2022). "The overexpression of c-MYC can enhance ribosome biogenesis to sustain the demand from cancer cells." (PMID 35267559, 2022). "While some cancers acquire amplification or overexpression of PHGDH, the first and rate-limiting step in this pathway, other types of cancers activate oncogenes such as MYC, MDM2, KRAS, and NRF2, leading to increased SSP enzyme expression." (PMID 35316216, 2022). "MYC is often persistently expressed in cancer, leading to the increased expression of genes involved in cell proliferation." (PMID 35370699, 2022). "The TF of MYC is a cancer driver that regulates many biological activities that contribute to tumorigenesis." (PMID 36077333, 2022). "Given the dependency on the TM of (super-enhancer driven) transcription, and subsequent transcriptional amplification by MYC, these TMi’s seem to be an effective strategy to indirectly target MYC-driven cancers." (PMID 36139513, 2022). "By doing so, BRD4 regulates the expression of genes that govern cell growth and evasion of apoptosis in cancer (e.g., MYC, BCL6, BCL2, and CDK4/6)." (PMID 35743155, 2022). "Over four decades of intense research activity have led to an advanced understanding of the physiological and pathological functions of MYC, uncovering it as a key pan‐cancer inducer of malignant phenotypes." (PMID 36214609, 2022). "Oncogenic MYC promotes glutamine uptake and glutaminolysis, creating an addiction to glutamine and sensitizing cancer cells to glutaminolysis inhibitors." (PMID 36214609, 2022). "As a famous oncogene at 8q24.21 region, MYC was identified as one of the core genes regulating stem cell-like properties of cancer cells." (PMID 36147475, 2022). "In accordance with our data in CRC cell lines, overexpression of miR-138 consistently downregulated MYC expression and in vitro cell growth of all three cancer types." (PMID 34937878, 2022). "While 4EBP1 is generally thought of as an inhibitor of protein translation, it is often overexpressed in cancer, suggesting its cooperation with c-MYC in the tumorigenesis." (PMID 35642054, 2022). "POU5F1 expression is controlled by several transcription factors, such as HIF1 and MYC, in cancer cells." (PMID 36564568, 2022). "For instance, by driving ER stress and enhanced activation of the UPR, the oncogene MYC contributes to the genesis of a variety of human cancers." (PMID 35205628, 2022). "According to previous studies, MYC is widely involved in many cancers, and its expression is estimated to be elevated or dysregulated in up to 70% of human cancers." (PMID 35075228, 2022). "The enrichment of gene sets of the G2/M checkpoint, E2F targets, and MYC targets in samples with a high R2 signature was also observed in the gene expression data of cancer cell lines from CCLE." (PMID 35794212, 2022). "c-MYC is a well-known oncogene and the other three factors are upregulated in multiple cancer types." (PMID 36361783, 2022). "As expected, MYC expressions in the cancer tissues were significantly upregulated, while CD247 and TLR2 were significantly downregulated in the adjacent normal tissues." (PMID 36389789, 2022).
cancer (continued). "Like POLR3G, high levels of MYC expression are associated with poor survival outcomes in specific and overlapping cancer contexts, evidence of concurrent MYC and Pol III dysregulation." (PMID 35637192, 2022). "Together, these findings indicate that SOX2 elevation downregulates the expression of MYC target genes in two diverse human cancer types." (PMID 35454854, 2022). "MYC, an important transcription factor in cancers, is also involved in the regulation of PD-L1 by EGFR." (PMID 35279217, 2022). "The discovery of the heterogenous MYC transcript population in cancer cells led us to focus on the identification of miRNAs, which target the MYC CDS as this is present in all MYC transcript variants." (PMID 34937878, 2022). "The CNV analysis by sequencing (CNV-seq) revealed five cancer-associated genes as the most frequent with gains (NOTCH1, MYC, NUMA1, PLAG1, and RAD21), while 30% of the tumors showed SMARCA4 with loss." (PMID 35884575, 2022). "In this study, we focus on the transcription factor MYC, which is overexpressed in more than half of all cancers." (PMID 34937878, 2022). "Taken together, AP4-induced MDC1 therefore limits the extent of DNA damage that cells encounter after activation of c-MYC and thereby allows the proliferation of cancer cells with deregulated c-MYC expression." (PMID 35624466, 2022). "The proto-oncogene MYC is a central regulator of cellular metabolism and is deregulated in over half of human cancers, including T-ALL, which relies on the TCA cycle and glutamine anaplerosis." (PMID 35740646, 2022). "In >50% of human cancers, the MYC transcription factor is involved, since this family of TFs control the expression of around 15% of the entire genome." (PMID 36497229, 2022). "These miRNAs, in aggregate, modulated key cancer-promoting genes and pathways, including the MYC oncogene (mark by asterisk) and pathways involved in viral carcinogenesis, MAPK signaling, and cell cycle." (PMID 36138741, 2022). "It was proposed that cancer cells with high MYC activity, which leads to an increased total RNA burden, rely on PRMT5 to orchestrate splicing fidelity." (PMID 35439169, 2022). "MYC is one of the well-known oncogenes, contributing to the development and progression of cancer and functions through interaction with MAX." (PMID 36167790, 2022). "Among these, LINC00824 (PVT1), which is adjacent to c-MYC gene and frequently upregulated in many cancers, was identified as a BRD4 target." (PMID 35399501, 2022). "In this study, we find that the MYC 3′UTR is shortened in cancer, and integrate two complementary computational and biochemical approaches to identify miRNAs that target the MYC coding region as this is present in all MYC transcript variants." (PMID 34937878, 2022). "Among TFs, MUC1-C induces MYC (c-MYC) in certain cancer cells and interacts with MYC in promoting the activation of MYC target genes." (PMID 35688945, 2022). "The MYC oncogene plays an important role in the tumorigenesis of many cancer types, is deregulated in >50% of human cancers, and is generally associated with unfavorable patient prognosis." (PMID 36479072, 2022). "A pharmacological approach to inhibit MYC in cancer cells is represented by Bromodomain and Extra-Terminal motif (BET) protein inhibitors." (PMID 35408939, 2022). "Recent studies have shown that the expression and function of MYC potentially help develop new cancer treatments." (PMID 35437508, 2022). "MYC is an important cancer-related transcription factor gene and sits on the most important gene node in the network, suggesting that it plays an important role in the antitumor mechanism of eucalyptol." (PMID 36331666, 2022).
cancer (continued). "The overexpression of MYC observed in approximately 70% of cancers is thought to be a critical step in tumorigenesis, and many of MYC’s specific oncogenic functions have been well defined." (PMID 36018850, 2022). "LncRNA PVT1 transcription site is located in a cancer susceptibility locus downstream of Myc, and ablation of PVT1 from MYC-driven colon cancer line HCT116 diminished its tumorigenic potency." (PMID 36266267, 2022). "Estrogens are thought to promote cancer cell proliferation through their interactions with regulatory components in the genome such as cyclin D and MYC." (PMID 35328602, 2022). "The effects of sanguinarine, quercetin, kaempferol, and thymoquinone were analyzed by monitoring c-MYC mRNA expression levels in cancer and immortalized cell lines." (PMID 36012470, 2022). "The findings of this study provide a valuable reference to revealing the mechanism of cancer-promoting action of MYC in LUAD." (PMID 36299592, 2022). "CCND1 and MYC are two typical target genes of β-catenin and these genes play an important role in cancer proliferation." (PMID 36336731, 2022). "Some of the most frequently activated oncogenes driving diverse cancers are c-MYC, EGFR, HER2, AKT, KRAS, BRAF, and MEK." (PMID 35594991, 2022). "The MYC transcription factor plays pleiotropic roles in cancer cells, both activating and repressing transcription, and the genome-wide binding of MYC to E boxes is biased towards H3K4me3-enriched sites." (PMID 35351824, 2022). "FN1, IL10, and MYC activation were related to the poor prognosis, indicating a pivotal role in cancer progression." (PMID 36389789, 2022). "The MYC oncogene and its product not only exert a central role in cancer initiation and progression, but are also generally recognized as negative prognostic factors in diverse malignancies." (PMID 36214609, 2022). "On the other hand, SENP1 has been shown to desumoylate MYC in cancer tissues, which can be suppressed by Momordin Ic (MI), resulting in cell cycle arrest and apoptosis in CRC cells." (PMID 35887358, 2022). "DNA replication stress resulting from the activity of oncogenes such as MYC, is a common feature of cancer cells." (PMID 36240065, 2022). "MYC-driven cancers were already known to be particularly vulnerable to splicing inhibition by SF3B-targeting compounds." (PMID 35406598, 2022). "Interactions between WD40 repeat domain protein 5 (WDR5) and its various partners such as mixed lineage leukemia (MLL) and c-MYC are essential for sustaining oncogenesis in human cancers." (PMID 34586829, 2021). "Numerous attempts have been employed to interfere with the oncogenic functions of the cancer driver MYC in order to obtain tools for efficient treatment of MYC-dependent tumors." (PMID 33937075, 2021). "Recently, transcription factors (Stat3, Smad, AP-1, NF-κB, E2F, MYC, Ets, Notch, FoxO, Wnt, Hdghog, miR-21, k-Ras) have attracted a fair share of attention as a novel drug target for cancer treatment." (PMID 34017038, 2021). "MYC and FOSL1 have previously been shown to be the two main effector targets that are downregulated due to BETi treatment in various cancers including LAC, with MYC reexpression being linked to multiple resistance mechanisms." (PMID 33712563, 2021). "Though MYC inhibition would be a powerful approach for the treatment of many types of cancers, the direct targeting of MYC has been a challenge for decades due to its “undruggable” protein structure." (PMID 33494392, 2021). "Targeting MYC has been suggested as a therapeutic strategy in several cancers, and many preclinical studies have demonstrated the potential anticancer effect of MYC inhibition." (PMID 33753878, 2021). "MYC plays an essential role in immune suppression and immune evasion mechanisms in assisting cancer cells to avoid the host’s immunity, as suggested in cancer studies." (PMID 33429951, 2021). "WNT/β-catenin, YAP, and PI3K/AKT signaling pathways are all promoters of MYC transcription in cancer cells." (PMID 34337362, 2021).